METTL1 (methyltransferase 1, tRNA methylguanosine)
Diseases named in the same sentence as METTL1 in open-access papers (continued):
Sharing a sentence is not in itself a finding about the gene and the disease.
cancer (continued). "Interestingly, it was discovered that knockdown of METTL1 did not alter mRNA levels of cancer-related genes, but its translation efficiency was impaired, leading to a drop in cell cycle-related proteins such as CCNA2, CCND2, CDK6, CDK8 and EGFR, which affected tumor progression." (PMID 37710294, 2023). "However, the relationship between METTL1 and cancer immune infiltration is not validated and the prognostic significance of METTL1 in pan-cancer remains unclear." (PMID 35432338, 2022). "Furthermore, the observation that the cytotoxic effect of 5-FU in yeast is enhanced by heat stress in a trm8 mutant strain leads us to the hypothesis that nonessential tRNA modifications catalyzed by NSUN2 and METTL1 impacts the efficiency of 5-FU treatment in human cancer cells." (PMID 25233213, 2014).
tumor (102 papers, 2012 to 2026). "In prostate cancer, METTL1 promotes tumorigenesis through the biogenesis of tRNA-derived fragments, while its deletion leads to the loss of m7G modification, inhibiting tumor growth." (PMID 41501031, 2026). "Recent studies have shown that METTL1 is closely associated with processes involved in the progression of diseases, including tumour proliferation, migration, invasion, angiogenesis, chemo‐ and radiotherapy resistance, energy metabolism and TIME suppression." (PMID 39979979, 2025). "Prior investigations have uncovered an association between METTL1 and immune checkpoint molecules, further supporting its role in tumor immunology." (PMID 40809384, 2025). "For example, METTL1 upregulation drives the differentiation of tumor-associated stromal cells, which in turn amplifies their immunosuppressive functions and reduces CD8+ T cell infiltration in HCC." (PMID 40809384, 2025). "METTL1 deficiency in tumor cells inhibits the m7G modification of 16 tRNAs, leading to a reduction in the global translation of oncogenic transcripts and subsequently inhibiting HNSCC progression." (PMID 39870616, 2025). "In CC, METTL1 overexpression has been associated with greater cisplatin sensitivity via the miR‐149‐3p axis, consistent with a tumour‐suppressive output of the m7G–miRNA programme in a therapeutic context." (PMID 41208200, 2025). "Bioinformatic analyses further indicate that METTL1 expression in invasive breast carcinoma is closely associated with disease diagnosis, prognosis, and tumor immune infiltration." (PMID 41562049, 2025). "Previous studies have shown that aberrant expression of METTL1 is closely associated with tumor development and patient survival." (PMID 40443650, 2025). "Loss of METTL1 leads to a reduced abundance of specific m7G -modified tRNAs that decode certain codons enriched in tumor-related mRNAs." (PMID 41562049, 2025). "Functional enrichment analyses reveal that elevated METTL1 is significantly associated with tumor progression–related pathways." (PMID 41562049, 2025). "Several studies have demonstrated that METTL1 is closely associated with the initiation, progression and prognosis of diseases other than tumours." (PMID 39979979, 2025). "In patients with HCC, elevated METTL1 expression is closely linked to advanced tumor stage and poor clinical outcomes." (PMID 39870616, 2025). "Here, we found that the expression of the m7G tRNA methyltransferase METTL1 is low in normal tissues but significantly upregulated in PTC tumor samples, and that high expression of METTL1 is associated with poor patient survival outcomes." (PMID 40360483, 2025). "Previous investigations have demonstrated that elevated METTL1 expression in tumour tissues is strongly associated with poor prognostic outcomes in HCC patients undergoing radiotherapy." (PMID 39979979, 2025). "In HCC, the overexpression of METTL1/WDR4 is associated with advanced‐stage tumours and a poor prognosis." (PMID 38943267, 2024). "In contrast, Mettl1-deficient tumours were encapsulated and predominantly comprised of luminal cells with low proliferative potential." (PMID 37660182, 2023). "Accordingly, Mettl1-deficient tumours exhibited a significant increase in apoptosis, leading to a substantial reduction in tumour mass." (PMID 37660182, 2023). "In HCC, METTL1 expression is closely associated with tumor malignancy and poor prognosis." (PMID 40809384, 2025). "METTL1 also plays a role in the polarisation of tumour‐associated macrophages (TAMs)." (PMID 39979979, 2025). "For example, in the IMvigor210 anti-PD-L1 treatment cohort, patients with favorable responses exhibited significantly higher METTL1 expression compared to non- or limited-response groups, and high METTL1 expression was generally associated with a higher tumor neoantigen burden." (PMID 41562049, 2025).
tumor (continued). "First, as a widely expressed RNA-modifying enzyme involved in maintaining translational homeostasis in normal cells, global inhibition of METTL1 may cause toxicity and off-target effects, necessitating strategies for tumor-specific targeting." (PMID 41562049, 2025). "The underlying mechanism suggests that METTL1 overexpression may promote tumor immune evasion by establishing an immunosuppressive microenvironment predominantly characterized by Tregs." (PMID 40809384, 2025). "Subsequently, in vivo studies on subcutaneous tumor xenografts in nude mice demonstrated that METTL1 knockdown could inhibit tumor growth, while overexpression of BRCA1 could reverse the inhibited tumor growth caused by METTL1 downregulation (all p < 0.0001)." (PMID 41430564, 2025). "Moreover, METTL1 is positively associated with immune cell infiltration in tumor microenvironments (TME)." (PMID 40809384, 2025). "Importantly, restoring ATF4 levels leads to glycolytic metabolic reprogramming in tumor cells and counteracts the anti-tumor effects caused by METTL1 knockdown." (PMID 40809384, 2025). "In addition, loss of METTL1 inhibits tumor growth, cell viability, and increases cytotoxic stress in the body." (PMID 39850560, 2024). "A strong association between METTL1 and tumor pathophysiology has been reported." (PMID 38967523, 2024). "Furthermore, METTL1 expression was found to be associated with tumor postoperative pathological grade in HCC." (PMID 39616161, 2024). "Thus, our data demonstrate that METTL1-deficient tumours fail to activate survival pathways in response to stress." (PMID 37660182, 2023). "Furthermore, we find that the loss of METTL1 reduces tumour growth and increases cytotoxic stress in vivo." (PMID 37660182, 2023). "To determine if the cytokine intratumoural composition in Mettl1-deficient tumours could enhance the efficacy of ICB therapy, we treated mice with anti-PD1 and anti-CTL4A antibodies." (PMID 37516825, 2023). "For example, METTL1, a m7G methyltransferase, its aberrant upregulation in tumors has been found to be linked to end-stage tumors and worse prognosis, and METTL1 can drive oncogenic transformation and accelerate tumor progression by promoting m7G tRNA modification." (PMID 36339001, 2022). "In addition, high expression of METTL1 is often associated with poor prognosis in tumor patients, and METTL1 depletion affects m7G tRNA modification and changes the cell cycle, which is negatively correlated with oncogenicity." (PMID 36003341, 2022). "As a result, it could be inferred that the overexpressed METTL1 made miR-760 increased causing tumor promoting." (PMID 36396627, 2022). "Moreover, some studies have shown that METTL1 was associated with the immunosuppressive tumor microenvironment and stemness indices, and that its expression reflected the sensitivity of immune checkpoint blockade (ICB) therapy." (PMID 36226166, 2022). "Moreover, the expression of METTL1 is significantly associated with high tumor grades and stages, suggesting the essential function of METTL1 in ESCC progression." (PMID 35304469, 2022). "Interestingly, here we found that the expression of m7G tRNA methyltransferase METTL1 is low in normal tissues but significantly upregulated in the ESCC tumor samples, and the high expression of METTL1 is associated with poor patient prognosis." (PMID 35304469, 2022). "Interestingly, METTL1 has been linked to tumor vascular invasion and poor prognosis in hepatocellular carcinoma." (PMID 34282776, 2021). "METTL1 is also a potential therapeutic target, and its silencing can inhibit the growth of tumor cells." (PMID 41501031, 2026). "This study underscores the pivotal role of TXNDC12 in modulating tumor biology and chemoresistance, positioning the METTL1-TXNDC12-c-Myc axis as a promising target for improving patient outcomes in HNSCC." (PMID 40750708, 2025).
tumor (continued). "Subsequently, qRT-PCR was employed to assess the mRNA level of METTL1 expression in tumor tissues, revealing a consistent increase in METTL1 mRNA levels in cSCC compared to normal skin tissues." (PMID 39870616, 2025). "Our results align well with these studies, showing that the overexpression of ATF4 significantly boosts glycolysis in METTL1-knockdown cSCC cells, indicating a connection between m7G modification and tumor glycolysis." (PMID 39870616, 2025). "In the current literature, studies investigating the role of METTL1 in tumor immunotherapy remain limited." (PMID 41562049, 2025). "METTL1 inhibits the function of CD8 + T immune cells and promotes tumor-associated macrophages (TAM) infiltration." (PMID 41194259, 2025). "Recent studies have revealed that METTL1-mediated tRNA m7G modification plays a critical role in the translational regulation of oncogenes and tumor progression in ICC." (PMID 41562049, 2025). "In short, METTL1 serves as a central regulator of diverse RNA modifications, profoundly influencing tumor initiation and progression." (PMID 40809384, 2025). "This regulatory mechanism promotes tumour cell proliferation and underscores the oncogenic potential of METTL1‐mediated m7G modification." (PMID 41208200, 2025). "In summary, this study enhances our understanding of the role of m7G RNA modification in tumor progression and highlights METTL1 as a novel therapeutic target and biomarker for SKCM immunotherapy." (PMID 40443650, 2025). "Additional analyses indicate that tumor cell lines with high METTL1 expression are more sensitive to drugs targeting chromatin-associated histone methylation, ERK-MAPK, and WNT signaling pathways." (PMID 41562049, 2025). "Inhibiting METTL1 led to reduced survival, migration, invasion, and xenograft tumor growth in cSCC cells." (PMID 39870616, 2025). "A recent study revealed that the levels of METTL1 and WDR4 are elevated in HCC and are associated with advanced tumour stages and poor patient survival." (PMID 39979979, 2025). "In HCC patient tissues, METTL1 and WDR4 expression levels are positively correlated, and their high expression is associated with advanced tumor stage and poor prognosis, suggesting a synergistic oncogenic role." (PMID 41562049, 2025). "TISCH database analysis showed that METTL1 expression was higher in metastatic malignant tumor cells." (PMID 40443650, 2025). "To further determine the spatiotemporal expression pattern of METTL1, we analyzed the relationship between METTL1 and the developmental chronology of tumor cells using monocle algorithm with two sets of single-cell sequencing data, GSE72056 and GSE174401." (PMID 40443650, 2025). "We initially found that the protein levels of METTL1 in the tumor tissues originating from METTL1-knockdown cells were significantly decreased than those originating from control cells." (PMID 39870616, 2025). "Specifically, global METTL1 levels in tumor tissues continued to rise with increases in tumor stage." (PMID 39870616, 2025). "In HCC, METTL1 overexpression was reported to be correlated with larger tumor sizes and poor prognosis, primarily by activating the PTEN/AKT signaling pathway." (PMID 40809384, 2025). "Meanwhile, RNA interference (RNAi) and CRISPR/Cas9 gene-editing technologies have been widely employed to validate METTL1 function, demonstrating that silencing or knockout of METTL1 can significantly suppress tumor cell proliferation and migration." (PMID 41562049, 2025). "METTL1 knockdown induced reduction in m7G levels of tRNAs that translate these oncogenic mRNAs, which inhibited tumor growth." (PMID 40809384, 2025). "Future research should focus on elucidating the context-dependent functions of METTL1 and developing individualized therapeutic strategies based on tumor-specific molecular characteristics." (PMID 41562049, 2025).
tumor (continued). "CRC development is influenced by multilayered epigenetic regulation, among which RNA m7G modification and its regulator METTL1 play critical roles in promoting tumor progression and modulating the tumor immune microenvironment." (PMID 41562049, 2025). "Together, these results confirmed that the m7G tRNA methyltransferases METTL1 and WDR4 are pathologically and clinically associated with tumor aggressiveness and poor survival outcomes in patients with PTC." (PMID 40360483, 2025). "In summary, this study reveals the tumour‐promoting role of METTL1‐mediated tRNA m7G modification in controlling NBL progression, providing a potential strategy for the clinical management of NBL." (PMID 39979979, 2025). "This review aims to systematically summarize the biological functions of METTL1, its roles in tumor development and tumor immunity, as well as current therapeutic attempts and future research directions." (PMID 41562049, 2025). "In HCT-116 xenograft models, METTL1 knockdown suppresses tumor growth, whereas RRP9 overexpression partially rescues this effect." (PMID 41562049, 2025). "For instance, METTL1-mediated translational reprogramming can alter antigen processing and presentation in tumor cells, thereby influencing immune recognition." (PMID 41562049, 2025). "Further evidence from overexpression and gene knockout mouse models demonstrates that METTL1-mediated tRNA m7G modification has a tumor-promoting role in ICC initiation and progression." (PMID 41562049, 2025). "Single-cell sequencing further reveals that METTL1 deletion alters the tumor immune microenvironment and cell–cell interactions between tumor and stromal compartments in mouse models." (PMID 41562049, 2025). "To further elucidate the potential involvement of METTL1 in tumor progression, we evaluated its protein and mRNA level along with m7G methylation levels in the cSCC cell lines (HSC-1 and A431) in comparison with control HaCaT keratinocytes." (PMID 39870616, 2025). "miR‐149‐3p has been identified as a tumour‐suppressive miRNA in LC, and METTL1 promotes its expression in an m7G‐dependent fashion, contributing to the inhibition of tumour progression." (PMID 41208200, 2025). "In vivo studies showed combined therapy with METTL1 overexpression significantly improved tumor suppression compared to monotherapies, correlating with elevated RB1/GADD45A levels and reduced Ki67." (PMID 40809384, 2025). "This demonstrates that METTL1-mediated tRNA m7G methylation is critical for translational control and tumor immune regulation, highlighting its potential as a therapeutically targetable molecule." (PMID 41562049, 2025). "Intriguingly, restoring ATF4 expression in cSCC cells not only promoted glycolysis but also reversed the anti-tumor effects of METTL1 knockdown." (PMID 39870616, 2025). "The upregulation of ATF4 in cSCC cells counteracted the anti-tumor effect of METTL1 knockdown by enhancing glycolytic capability in cSCC cells." (PMID 39870616, 2025). "Recent studies have expanded the scope of METTL1’s functions, revealing its ability to modify mRNA, thereby promoting tumor growth through enhanced mRNA stability and translation." (PMID 40750708, 2025). "METTL1 influences tumor cell survival and programmed cell death by regulating the immune microenvironment." (PMID 39802639, 2025). "Recent studies further indicate that METTL1 not only affects intrinsic tumor cell biology but also modulates the tumor immune microenvironment." (PMID 41562049, 2025). "Further in vivo experiments demonstrated that METTL1 overexpression enhances the anti-tumor efficacy of the CDK4/6 inhibitor abemaciclib." (PMID 41562049, 2025). "Nude mice injected with METTL1-knockdown cells had significantly slower tumor growth and lower tumor volume and weight than did those injected with parental control cells expressing METTL1." (PMID 40360483, 2025).